GZMA (granzyme A)
Description:
Abundant protease in the cytosolic granules of cytotoxic T-cells and NK-cells which activates caspase-independent pyroptosis when delivered into the target cell through the immunological synapse. It cleaves after Lys or Arg. Once delivered into the target cell, acts by catalyzing cleavage of gasdermin-B (GSDMB), releasing the pore-forming moiety of GSDMB, thereby triggering pyroptosis and target cell death. Cleaves APEX1 after 'Lys-31' and destroys its oxidative repair activity. Cleaves the nucleosome assembly protein SET after 'Lys-189', which disrupts its nucleosome assembly activity and allows the SET complex to translocate into the nucleus to nick and degrade the DNA.
Synonyms: CTLA3; HFSP
Tractability: Small molecule: a structure with a bound ligand is known; a high-quality ligand is known; it has a binding pocket of medium quality. Antibody: UniProt places it where antibodies can reach, with high confidence; UniProt predicts a signal peptide or a membrane-spanning region; its Gene Ontology location is reachable by antibodies, with medium confidence. PROTAC: ubiquitination databases record sites on it; its protein half-life has been measured.
Target class: Serine protease; Enzyme; Serine protease PA clan; Serine protease S1A subfamily; Protease
Gene: Protein-coding gene on chromosome 5 (55,102,646 to 55,110,252, forward strand). Ensembl gene ENSG00000145649.
Subcellular location: Secreted (Isoform alpha); Cytoplasmic granule
Gene Ontology:
Molecular function: protein binding; protein homodimerization activity; serine-type endopeptidase activity; serine-type peptidase activity
Biological process: cytotoxic T cell pyroptotic cell death; granzyme-mediated programmed cell death signaling pathway; positive regulation of apoptotic process; protein catabolic process; protein maturation; pyroptotic inflammatory response; apoptotic process; immune response; proteolysis
Cellular component: cytoplasm; extracellular region; immunological synapse; nucleus; cytolytic granule
Genetic constraint (gnomAD): Loss-of-function variants: 12 observed, 15.37 expected, observed/expected ratio (o/e) 0.78, 90% interval 0.5 to 1.26. The synonymous counts are far from expectation, so gnomAD's model fits this gene poorly and the ratio says little. Missense variants: 242 observed, 255.44 expected, observed/expected ratio (o/e) 0.95, 90% interval 0.85 to 1.05. Synonymous variants: 62 observed, 85.3 expected, observed/expected ratio (o/e) 0.73, 90% interval 0.59 to 0.9.
Homologues: Orthologues: chimpanzee GZMA (98% identical), macaque GZMA (91% identical), pig GZMA (73% identical), rat Gzma (70% identical), guinea pig GZMA (69% identical), mouse Gzma (68% identical), tropical clawed frog gzma (43% identical), Drosophila melanogaster CG14780 (29% identical), Drosophila melanogaster CG33225 (26% identical), Drosophila melanogaster CG33226 (26% identical), Drosophila melanogaster CG30283 (25% identical), Drosophila melanogaster CG30289 (25% identical), and 6 more. Paralogues in human: GZMK (41% identical), HABP2 (36% identical), HGF (26% identical), MST1 (26% identical), PIK3IP1 (13% identical).
Diseases named in the same sentence as GZMA in open-access papers:
GZMA is named in the same sentence as 177 diseases in open-access papers, as found by Europe PMC text mining. Sharing a sentence is not in itself a finding about the gene and the disease. The quoted sentences say what the papers report.
COVID-19 (36 papers, 2020 to 2025). A disease caused by infection with severe acute respiratory syndrome coronavirus 2. "Validation to these findings was observed during the recent COVID-19 pandemic, in which NK cells derived from severe COVID-19 patients, compared to healthy patients showed reduced expression of granzyme A that was associated with IL-6 serum levels, in addition to reduced perforin expression." (PMID 33815404, 2021). "•PPI-identified hub genes IL7R/CD2/GZMA/CD3D/FCER1A diagnose COVID-19 and diabetic nephropathy with AUC>0.80, linking immune activation to tissue damage." (PMID 41332907, 2025). "The expression of cytotoxic effector molecules like perforin and Granzyme A are also significantly increased during most COVID-19 cases." (PMID 37928543, 2023). "In fatal COVID-19 cases, patients had impaired upregulation of perforin, granzyme-A, and KI-67, suggesting that defects in NK cell cytotoxic activity are associated with increased morbidity and mortality." (PMID 37928543, 2023). "Upregulated genes in late COVID-19 mortality included those involved in pyroptosis (e.g., GZMA, CASP1) and fibrosis (COL1A1)." (PMID 35446789, 2022). "In detail, the frequency of GzmA+GzmB+perforin+ cells co-expressing lung-homing receptors was commonly strongly increased in patients, except for CD56dimCD16+ NK cells in COVID-19 patients." (PMID 35371005, 2022). "On the other hand, a reduction in the production of IFN-γ and granzyme A in CD4+ T lymphocytes in patients with COVID-19 was also reported in another study, indicating a functional change." (PMID 36359755, 2022). "A controversial role is played in COVID-19 by CD8+ T cells with reduced levels of CD107a, IFN-γ, IL-2, and granzyme B compared to healthy cells, or by CD8+ T cells with increased production of granzyme A and B and perforin during COVID-19." (PMID 36359755, 2022). "In the patients with moderate COVID-19, CD8+ TTE cells showed higher expression of IFNG, TNF, CCL5, PRF1, GZMB, and GZMA, together with genes encoding cytotoxic receptors (KLRB1, KLRC1, and KLRD1) in comparison with severe cases." (PMID 36119105, 2022). "Another study suggested that decreased perforin and granzyme A levels in CD4+ T cells, CD8+ T cell and NK cells is associated with severely afflicted COVID-19 patients." (PMID 34075347, 2021). "Conversely, in elderly COVID-19 patients, there was a reduced expression of granzyme A and perforin." (PMID 34075347, 2021). "In particular, IL-6 directly reduces the expression of perforin and granzyme B. In patients with COVID-19 admitted to the intensive care unit, an inverse correlation between serum levels of IL-6 and NK cells’ frequency of expressing granzyme A was found." (PMID 33669527, 2021). "COVID-19 patients had higher frequencies of CD8+ T cells producing the cytotoxic molecules GzmA and GzmB as well as perforin than healthy controls." (PMID 32948688, 2020). "GZMA involvement in both COVID-19 and DN indicates a potential shared pathway for immune-mediated tissue damage, which may exacerbate kidney damage in patients with COVID-19." (PMID 41332907, 2025). "Indeed, NK cells and CD8+ T cells in BAL fluid from COVID-19 patients displayed increased transcript expression levels of GZMA, GZMB, and PRF1 even in patients with moderate disease." (PMID 35371005, 2022). "Additionally, it is worth noting that activated CD38+HLA-DR+CD8+ T cells from acute COVID-19 patients contained higher levels of intracellular granzyme A and B along with perforin proteins vs. convalescent COVID-19 patients or control subjects." (PMID 36146713, 2022). "In a study using HLA-A02 tetramer, antigen-specific CD8+ T cells (obtained from COVID-19 acute-phase patients) responding to the S269–277 epitope of the spike protein predominantly belonged to the subpopulation simultaneously expressing GZMA, GZMB, GZMK, and perforin." (PMID 36685601, 2022).
COVID-19 (continued). "More importantly, elevated expression of regulatory molecules, such as CD244 and programmed death-1 (PD-1), on NK cells and T cells, as well as decreased serum cytotoxic effector molecules including perforin and granzyme A, were detected in patients with COVID-19." (PMID 33154753, 2020). "Thus, decreased granzyme A and perforin could be implicated in reduced ROS production for the impaired effectiveness of CD8+ T cells in either convalescent patients or COVID-19 patients." (PMID 34075347, 2021). "For COVID-19, the AUCs of IL7R, CD2, GZMA, CD3D, and FCER1A were 0.925, 0.934, 0.905, 0.950, and 0.998, respectively." (PMID 41332907, 2025). "Patients with mild COVID-19 exhibited expanded subsets of unconventional CD56dimCD16- NK cells with elevated NKG2D expression and lower levels of cytotoxic mediators (granzyme A, granzyme B, and granulysin)." (PMID 40421029, 2025). "Both granzyme A and B positive CD8+ T cells were more activated (increased CD69 expression) in all COVID-19 patients compared to the control group." (PMID 39764446, 2024). "We found that NKG7, IL32, GZMA, PRF1, CST7, GZMH, and CCL5 were among the top DEG downregulated in CD3+ upon nasal Foralumab treatment of COVID-19 subjects." (PMID 36881624, 2023). "COVID-19 patients with encephalopathy had significant overexpression of various cytotoxic genes, including PRF1, GZMK, GZMA, GZMB, GNLY, and CST7." (PMID 37848421, 2023). "COVID-19 patients, particularly those with severe COVID-19, show impaired antiviral responses with decreased CD3+ T cells and NK cells, reduced perforin and granzyme A expression, and increased IL-6 serum levels." (PMID 37369668, 2023). "Similar to GZMA, PRF1, GZMK and GZMB in T cells, significant increases in CASP3 were also present in COVID-19 patients with encephalopathy, and the highest expression of this gene was observed in acute necrotizing encephalopathy patients." (PMID 37848421, 2023). "Whereas NK cells from COVID-19 WARD patients show an increase in PRF, GZMA, and GZMB, levels were decreased in ICU patients." (PMID 36275702, 2022). "NK4 cells in COVID-19 exhibited cytolytic potential with increased expression of granzymes (GZMB and GZMA) and expressed CD56." (PMID 34721400, 2021). "In this study, we analyzed the gene expression pattern of cytotoxic proteins (PRF1, GZMB, GNLY, GZMA, GZMK), cytokine (IFN-γ), and apoptotic protein (FASL) in CD8+ T cells from the peripheral blood of COVID-19 patients." (PMID 34945761, 2021). "Another study found that young COVID-19 patients had greater percentages of CD8+ T cells expressing perforin, granzyme A, and granzyme B compared to healthy controls of the same age, but the same difference was not seen in elderly COVID-19 patients." (PMID 36817450, 2023). "Regardless of myopericarditis development, the COVID-19 mRNA vaccine caused an increase of NK cell number and gene expression associated with effector function such as IFN-γ (IFNG), granzyme A (GZMA), and granzyme B (GZMB) compared with healthy controls." (PMID 35251049, 2022). "TH1-like cells from patients with mild COVID-19 exhibited a TH1 polarization state, characterized by upregulation of effector marker genes (PDCD1, CCL5, CXCR2, CCR2, GZMA/B, NKG7, PRF1, IFNG, and CCL4) and genes involved in effector function such as CXCR4, CXCL2, ANXA1, SOCS2 and LTB." (PMID 36119105, 2022). "This should be the case, as taurine levels are generally increased during active infection in mild/moderate patients compared to healthy controls and are not specifically decreasing due to granzyme A and perforin lacking ROS activity in COVID-19 patients." (PMID 34075347, 2021). "COVID-19, CD8+ T cells, Granzyme A, Perforin, Metabolites, 1H-NMR, Flow cytometry." (PMID 34075347, 2021).
COVID-19 (continued). "To characterize their cytotoxic profile, we stained the total CD4+ T cells directly ex vivo without restimulation for the cytotoxic molecules GzmA, GzmB, and perforin and compared the two age groups between COVID-19 patients and age-matched healthy controls." (PMID 32948688, 2020). "In addition to robust cytotoxic T cell functions, enrichment of KLRB1, GZMA, and GZMK transcripts may indicate enhanced NK cell cytotoxic activity in Δ382 SARS-CoV-2 infected patients, in which the function is impaired in severe COVID-19 patients." (PMID 34716845, 2022).
melanoma (24 papers, 2017 to 2026). A malignant, usually aggressive tumor composed of atypical, neoplastic melanocytes. "Our findings indicate a positive correlation between tumor‐intrinsic IL4I1 expression and the expression of HLA‐A/‐B/‐C, B2M, and genes associated with CTL activation (GZMB, GZMA, CD8A, IFNG) in melanoma patients." (PMID 40583248, 2025). "By combiningγδ-T exosomes and PDT, we achieved a robustantitumor effect from γδ-T exosome-derived cytolytic molecules,including granzyme A, granzyme B, perforin, and granulysin, and Ce6-mediatedROS generation inside melanoma cells." (PMID 39862206, 2025). "Lower expression of GzmA in patients with melanoma treated with checkpoint inhibitors predicted an unfavorable prognosis, whereas high expression correlated with CD8+ T cell infiltration." (PMID 39436696, 2024). "In combination, the findings suggested that GZMA, GSDMB, NLRP1, CHMP4A, and IL18 deficiency, at least in part, are responsible for melanoma." (PMID 37620327, 2023). "Histologically, melanoma tissues had fewer positive cells percentage of pyroptosis-related genes (PRGs), GZMA, GSDMB, NLRP1, IL18, and CHMP4A in epidermal than in normal skin." (PMID 37620327, 2023). "Histologically, melanoma tissues had fewer positive cells percentage of PRGs, GZMA, GSDMB, NLRP1, IL18, and CHMP4A in epidermal than in normal skin." (PMID 37620327, 2023). "Conversely, the expression of GZMA in CD57+ cells within melanoma specimens was minimal, measuring merely 0.15%." (PMID 37620327, 2023). "Melanoma specimens secreted a minimal presence of GZMA+ merged CD8+ T cells (0.11%) and GSDMB+ merged CD57+ cells (0.08%), compared to the control groups exhibiting proportions of 4.02% and 0.62%, respectively." (PMID 37620327, 2023). "What stands out in this table is that GZMA almost clustered together in melanoma samples, especially in CD8 + T cells and NK cells." (PMID 37620327, 2023). "NLRC5 expression was significantly positively associated with both CYT score and the expression of PRF1 and GZMA in all four melanoma datasets." (PMID 34307322, 2021). "(2016) identified a link between enhanced Mes features in ESRP1‐low melanoma and high infiltrating lymphocyte activity, as assessed by a two‐gene signature (PRF1 encoding for perforin and GZMA encoding for granzyme A)." (PMID 28614624, 2017). "With GZMA expressed by significantly higher percentages of mucosal CD8 + T cells, findings suggest that melanoma harboring high GZMA expression may respond preferentially to cancer immunotherapies." (PMID 37620327, 2023). "GZMA exhibited medium protein expression in the majority of the pancreatic cancers (70%), in <35% of breast, cervical, liver, ovarian, prostate, renal, stomach, testis, and urothelial cancers, as well as in <10% of lymphomas and melanomas." (PMID 29515971, 2018). "Finally, in a study of 54 melanoma patients treated with tumor-infiltrating lymphocyte (TIL) therapy, TIL products showing high expression of memory-associated genes and low expression of granzyme A (GZMA) and interferon gamma (IFN-γ) correlated with response." (PMID 37880715, 2023). "Although the clinical evidence implied that melanoma skin tissue reduced GZMA, GSDMB, NLRP1, IL18, and CHMP4A expression in epidermal, however, the result obtained with bulk-sorted samples could not explain the main scientific questions on cell sources heterogeneity." (PMID 37620327, 2023). "In addition, mice vaccinated with T/O cell-associated OVA and GzmA were protected against the MO4 (OVA-expressing B16 melanoma) tumor (left), but not against the parental B16 tumor (right), demonstrating the antigen specific antitumor effect." (PMID 31293597, 2019). "The coexistence of reduced expression percentages of GZMA+ cells in tumor CD8+ T cells also suggests a diminished immune checkpoint and cellular cytotoxicity in melanoma." (PMID 37620327, 2023).
melanoma (continued). "The co-expression of CD8 and GZMA was prominently observed in control specimens at a rate of 4.02%, whereas the expression of GZMA in CD8+ T cells in melanoma specimens was minimal, measuring only 0.11%." (PMID 37620327, 2023). "The presence of decreased expression levels of GZMA+ cells within tumor CD8+ T cells further implies a weakened immune checkpoint and diminished cellular cytotoxicity in melanoma." (PMID 37620327, 2023). "GZMA and GSDMB could be regarded as significant indicators of immune therapeutic strategies of melanoma." (PMID 37620327, 2023). "The initial findings from the enzyme-linked immunosorbent assay (ELISA) indicated a statistically significant downregulation of pyroptosis protein expression in melanoma patients when compared to the control group, especially NLRP1, GZMA, and GSDMB, followed by CHMP4A and IL18." (PMID 37620327, 2023). "Multiplex immunofluorescence staining results furtherer confirmed GZMA+ cells and GSDMB+ cells are secreted by CD8 + T cells and NK cells, suggesting ruduced tumor immune cells leading to lower pyroptosis capability on anti-melanoma properties." (PMID 37620327, 2023). "In addition to PD-L1 expression, we found that the higher expression of granzyme A (GZMA) and HLA-A was observed in pretreated tissues of melanoma patients who responded to anti-PD-1 therapy, which can be potential biomarkers to expect clinical responses." (PMID 34369137, 2021). "The expressions of CD8A, GZMA, GZMK and PRF1 genes in the NOS1-high-expression group were significantly lower than those in the NOS1-low-expression group, indicating that NOS1 might play an immunoregulatory role only in “cold” melanoma." (PMID 41535256, 2026).
breast carcinoma (18 papers, 2015 to 2025). "Similarly, the expression of GZMA in breast cancer is associated with malignant features, while low GZMA expression is related to higher tumor grade, lymph node metastasis, and worse prognosis." (PMID 37884883, 2023). "The association between GZMA mutations and survival outcomes in BRCA aligns with studies emphasizing the role of immune-related genes in breast cancer prognosis." (PMID 40002821, 2025). "Based on multivariable Cox regression analysis, GZMA was identified as an independent favorable prognostic factor for breast cancer." (PMID 38833021, 2024). "Overall, kidney and breast cancers displayed the highest expression of GZMA, GZMB, GZMK and PRF1." (PMID 40002821, 2025). "Moreover, our results showing the importance of GZMA in breast cancer is further supported by research showing better survival rates among patients with high GZMA expression." (PMID 40002821, 2025). "Collected from murine breast cancer models or when cocultured with breast cancer cells, uptake of tumor‐derived cAMP markedly increased SA‐β‐Gal+ NK cells, along with impaired expression of effector molecules like granzymes A/B (GZMA/B), perforin, and IFN‐γ." (PMID 41427020, 2025). "In summary, GZMA plays an important role in hepatocellular carcinoma and breast cancer." (PMID 37884883, 2023). "Furthermore, quantitative immunofluorescence analysis has demonstrated a positive association between GZMA expression and the presence of dendritic cells and CD8+ T cells infiltrating breast cancer tissue." (PMID 37760494, 2023). "Bioinformatics analysis of in silico publicly available TNBC data identified BCL3 and BCL2 as well as the following anti-tumour immune response biomarkers as significantly altered in TNBC compared to other breast cancer subtypes: GZMA, PRF1, CXCL1, CCL2, CCL4, and CCL5." (PMID 38022682, 2023). "Therefore, the results in TCGA cohort demonstrated that GZMA, GZMB, and IFNG in the low-risk group were highly expressed, while TGFB1 was elevated in high-risk breast cancer patients (p < 0.001)." (PMID 35619902, 2022). "Additionally, higher levels of GZMA may represent higher levels of cytotoxic T-cell infiltration, leading to better survival rates of breast cancer." (PMID 36479102, 2022). "Recent studies have shown that GZMA plays a significant role in hepatocellular carcinoma (HCC) and breast cancer." (PMID 37884883, 2023). "Although the apoptosis mechanisms mediated by GZMA and GZMB are well-documented, the roles of other granzymes, especially GZMK, which exhibits trypsin-like catalytic activity, are less understood in Tc-mediated cytotoxicity, particularly in breast cancer." (PMID 38833021, 2024). "Additionally, a correlation has been observed between GZMA and T-cell checkpoints, including PD-1, PD-L1, and CTLA-4, in breast cancer." (PMID 37760494, 2023).